ERG (ETS transcription factor ERG)
Diseases named in the same sentence as ERG in open-access papers (continued):
Sharing a sentence is not in itself a finding about the gene and the disease.
colorectal cancer (10 papers, 2014 to 2025). A primary or metastatic malignant neoplasm that affects the colon or rectum. "ERG is a target of miR-145 in colorectal cancer and prostate cancer." (PMID 32591615, 2020). "However, the knockdown of the lncRNA STEAP3-AS1 significantly reduced the binding of BRG1, ERG, P300, and H3K18la, indicating that the lncRNA STEAP3-AS1-mediated BRG1/ERG/P300 complex regulates the H3K18la-specific activation of MMP9, which is a key to colorectal cancer liver metastasis." (PMID 40665344, 2025).
Down syndrome (10 papers, 2009 to 2025). "ERG encodes a member of the Ets family of transcription factors, and is known to be included in the Down syndrome critical region on chromosome 21." (PMID 21738478, 2011). "Misclassification incidents involving FUS::ERG fusions, KMT2A rearrangements in older adults, and Down Syndrome-associated AML highlight critical gaps in training data availability." (PMID 40730747, 2025). "Co-expression of ERG and the short isoform of Gata1 (Gata1s, universally expressed in Down syndrome’s myeloid malignancies), led to transient myeloproliferative disorder and acute megakaryocytic leukemia (AMKL) in mice." (PMID 37735473, 2023). "An excess copy of the gene, ERG, an ETS family transcription factor, has been implicated in abnormal blood system development in Down syndrome." (PMID 25973911, 2015). "As the ERG gene is located on chromosome 21, it has been speculated that ERG expression may play a role in the pathogenesis of acute leukemia in patients with Down's syndrome." (PMID 19490647, 2009). "The human ERG gene belongs to the ETS family of transcription factors and is located on the long arm of chromosome 21 within the Down syndrome critical region." (PMID 37735473, 2023). "ETS2, one of the members of the ETS family as ERG, was previously characterized as a proto-oncogene in AMKL children that is Down-syndrome and non-Down-syndrome-related, but the expression and clinical prognosis of ETS2 in AML remains unknown." (PMID 28724426, 2017).
glioma (9 papers, 2013 to 2024). A benign or malignant brain and spinal cord tumor that arises from glial cells (astrocytes, oligodendrocytes, ependymal cells). "Overall, a perturbed ERG expression could influence spliceosome formation and ribosome activity, thereby affecting the cell cycle, glioma cell proliferation and, ultimately, OS." (PMID 35299740, 2022). "Like in gliomas and HBs, in AVMs, HPCs, meningiomas, metastatic carcinomas, schwannomas, and SFTs, the nuclei of the endothelial cells lining vascular lumens demonstrated strong immunoreactivity for ERG." (PMID 25881913, 2015). "The RNA sequencing analysis of 140 samples of the two cohorts ‘gliomas and BM revealed samples with gene rearrangements that involve NTRK3, FGFR3, ERG, EGFR, or MET genes in seven samples (5%)." (PMID 39087020, 2024). "There were multiple, cancer type–specific hot spots of junctions located near known oncogenes such as KIT, PDGFRA, EGFR, CDK4, MDM2 (glioma), TMPRSS2, ERG (PCa), FGFR1, and CCDN1 (BrCa)." (PMID 34891161, 2021). "Another ETS-related gene, ERG, was found to be a novel and highly specific marker for endothelial cells within CNS tumors, a feature that can be used in studying the vascularization of gliomas." (PMID 33671331, 2021).
invasive carcinoma (9 papers, 2010 to 2024). A carcinoma that is not confined to the epithelium, and has spread to the surrounding stroma. "On the contrary, ERG immunoexpression appears to correlate with the tumor grade of invasive carcinoma with its positivity linked to low-grade tumors." (PMID 37185705, 2023). "According to our findings, the ERG immunopositivity of the IDCP-adjacent low-grade invasive carcinoma cannot be a fundamental immunophenotypic characteristic related to the cancerous clone within IDCP." (PMID 37185705, 2023). "TMPRSS2:ERG fusion is known to play a critical role in driving the progression from prostatic intraepithelial neoplasia (PIN) to invasive carcinoma." (PMID 36980776, 2023). "Altogether, the following studies largely demonstrated that IDC-P was distinct from HGPIN but similar to AIP and adjacent invasive carcinoma, at least in terms of ERG and PTEN expression." (PMID 35159086, 2022). "Immunohistochemistry (IHC) showed low ETS-related gene (ERG) positivity prevalence (1/15), with partial or complete loss of PTEN in roughly half the cases (7/15), and 56% of discordance for the nine cases with sufficient tissue to evaluate adjacent invasive carcinoma." (PMID 35159086, 2022). "Another important area of IDC-P research is the comparison between cases with and without IDC-P, especially since the studies established (mostly with ERG and PTEN expression patterns) that IDC-P was similar to its adjacent invasive carcinoma." (PMID 35159086, 2022). "Furthermore, we displayed a possible clonal relationship between the neoplastic cells of precursor lesions (HGPIN) and the adjacent invasive carcinoma based on PTEN expression patterns, and among IDCP and the abutting invasive cancer, based on ERG expression." (PMID 37185705, 2023). "Characteristically, in our study, when IDCP expressed ERG, the adjacent invasive carcinoma was also ERG-positive and paradoxically low-grade, whereas when IDCP lacked ERG expression, the abutting invasive component was ERG-negative and high-grade." (PMID 37185705, 2023).
epithelioid angiosarcoma (8 papers, 2022 to 2025). "To date, CD34, CD31, and ERG are the most frequently used endothelial markers for epithelioid angiosarcoma, as demonstrated by immunohistochemistry." (PMID 39958141, 2025). "Given the acknowledged limitation of CD34 in terms of specificity, it is prudent to adopt a comprehensive approach that incorporates the assessment of CD34 alongside CD31, ERG, F8, and additional pertinent markers for an accurate diagnosis of epithelioid hemangioendothelioma (EHE)." (PMID 40919137, 2025). "There was positivity for ERG, CD34, CD31, factor VIII, and c-myc, confirming the diagnosis of an epithelioid angiosarcoma." (PMID 39958141, 2025). "CD31, ERG, vimentin, factor VIII-related antigen, and Ulex europaeus agglutinin-1 (UEA-1) are sensitive and reliable markers for the immunohistochemical evaluation of epithelioid angiosarcoma." (PMID 35224706, 2022). "CD31expression has been reported to be a more specific marker of endothelial differentiation than CD34, and ERG has high sensitivity for detecting vascular differentiation, so CD31 and ERG staining may be suitable for the diagnosis of epithelioid angiosarcoma." (PMID 35310717, 2022). "The renal EAS is easily misdiagnosed as epithelioid hemangioendothelioma (EHE), as it could show similar characteristics in immunohistochemical staining, such as being positive for CD31, CD34, and ERG, but the results of Ki-67, WWTR1-CAMTA1, and YAP1-TFE3 might be helpful in differential diagnosis." (PMID 39687884, 2024).
gastric cancer (8 papers, 2013 to 2025). A primary or metastatic malignant neoplasm involving the stomach. "In the case of gastric cancer, paRNA_Ets-1 promotes the activation of ERG-related transcriptional processes by affecting the physical interaction between the NONO RNA-binding protein and the ERG transcription factor." (PMID 40002172, 2025). "SETDB1 mediates the malignant biological behaviour of gastric cancer by interacting with ERG and enhancing the promoter activity of CCND1 and MMP9." (PMID 38317200, 2024). "A histone lysine methyltransferase, SETDB1, which is upregulated in gastric cancer tissue, interacts with ERG (Ets-related gene) transcription regulator to promote the transcription of MMP-9 and cyclin D1 through binding to their promoter regions." (PMID 35163805, 2022). "The ERG expression was positively correlated with that of Ets-1 in these gastric cancer specimens (R = 0.760, P < 0.001)." (PMID 29773901, 2018). "High levels of pancEts-1, NONO, ERG, or Ets-1 were respectively associated with poor survival of gastric cancer patients, whereas simultaneous expression of all of them (HR = 3.012, P = 0.105) was not an independent prognostic factor for predicting clinical outcome." (PMID 29773901, 2018). "In addition, we identify that pancEts-1 is essential for the interaction between NONO and ERG, which results in ERG transactivation and Ets-1 upregulation that are associated with gastric cancer progression." (PMID 29773901, 2018). "Elevated GGH expression was found in breast, ERG-negative prostate, gallbladder, and gastric cancers compared to matched noncancerous tissues." (PMID 35082830, 2021). "The interaction between NONO and panc-Ets-1 promotes ERG transactivation on the Ets-1 promoter, thus supporting the aberrant growth of gastric cancer cells." (PMID 32722129, 2020). "Western blot and real-time qRT-PCR assays revealed the upregulation of NONO and ERG in gastric cancer specimens, especially in those with metastasis, than that in normal and precancerous gastric mucosa." (PMID 29773901, 2018). "Stable knockdown or ectopic expression of pancEts-1 attenuated and facilitated the binding of ERG to Ets-1 promoter in gastric cancer cell lines, which was rescued by transfection of NONO or sh-NONO #2, respectively." (PMID 29773901, 2018). "LncRNA pancEts-1 directly interacts with NONO to increase its interaction with ERG, resulting in transactivation of ERG, increase of Ets-1 expression, and promotion of the tumorigenesis and aggressiveness of gastric cancer cells." (PMID 29773901, 2018). "Mechanistically, pancEts-1 facilitated the physical interaction between NONO and Ets related gene (ERG), resulting in increased ERG transactivation and transcription of Ets-1 associated with gastric cancer progression." (PMID 29773901, 2018). "Overall, these results demonstrate that lncRNA pancEts-1 exhibits oncogenic properties that drive the progression of gastric cancer via regulating the NONO/ERG/Ets-1 axis." (PMID 29773901, 2018). "Higher NONO or ERG expression was also detected in cultured gastric cancer cell lines." (PMID 29773901, 2018). "Notably, simultaneous expression of NONO and ERG was observed in 48/81 (59.3%) gastric cancer specimens." (PMID 29773901, 2018). "Panc-Ets1 promotes tumorigenesis and aggressiveness of gastric cancer cells interacting with NONO and favoring ERG-positive transcriptional activity on ETS-1 gene." (PMID 32722129, 2020). "In gastric cancer, the interaction of pancEts-1 with NONO and ERG promotes ERG transactivation and upregulation of ETS-1 expression, which contributes to aberrant proliferation and invasiveness of gastric cancer cells." (PMID 32722129, 2020). "The recruitment of a multimolecular complex composed by pancEts-1/NONO/ERG on the Ets-1 gene drives ETS-1 expression and contributes to tumorigenesis and gastric cancer progression." (PMID 32722129, 2020).
gastric cancer (continued). "In our series of 81 gastric cancer cases, univariate analysis revealed that the levels of either pancEts-1 (P < 0.001), NONO (P = 0.003), ERG (P < 0.001), or Ets-1 (P < 0.001) were respectively associated with poor survival of patients." (PMID 29773901, 2018). "In this study, we demonstrate that ERG serves as a crucial transcriptional regulator that promotes the expression of Ets-1, while NONO functions as a coactivator of ERG in gastric cancer." (PMID 29773901, 2018). "In gastric cancer tissues, pancEts-1, NONO, and ERG were upregulated and significantly correlated with Ets-1 levels." (PMID 29773901, 2018). "Notably, the expression levels of ERG (R = 0.649, P < 1.0 × 10−4) or NONO (R = 0.644, P < 1.0 × 10−4) were positively correlated with those of Ets-1 in gastric cancer specimens." (PMID 29773901, 2018).
liver fibrosis (8 papers, 2017 to 2025). "Loss of the ubiquitous endothelial transcription factor ERG caused endothelial-mesenchymal transition in LSECs and led to the development of periportal liver fibrosis." (PMID 40810103, 2025). "ERG deficiency in liver EC results in endothelial-to-mesenchymal transition (EndMT) and spontaneous liver fibrosis by a shift from SMAD1 signaling to pro-fibrotic SMAD2/3 activity." (PMID 33745018, 2021). "Furthermore, the loss of ERG expression could be a sensitive marker of inflammation-driven fibrogenesis and a novel biomarker for EndoMT in human liver fibrosis." (PMID 35130955, 2022). "Additionally, these ERG/Gata1s mice demonstrated liver fibrosis and postnatal transient expansion of megakaryocytic progenitor cells, demonstrating that interaction between increased ERG expression and Gata1s is sufficient to cause a disease with key features of TAM in a murine model." (PMID 33777792, 2021). "Transcription factors other than c-Maf that determine LSEC differentiation, such as GATA4 or ERG, are known to be downregulated in human patients with liver fibrosis and cirrhosis." (PMID 40810103, 2025). "In a murine model of acute and chronic CCL4-induced liver fibrosis, we observed a rapid, marked and persistent reduction in ERG expression." (PMID 29026072, 2017). "TNF-α blockade protects ERG expression and reduces phosphorylation of SMAD2/3 in an acute model of liver fibrosis, but is ineffective in ERG hemi-deficient mice." (PMID 29026072, 2017). "The transcription factor ERG controls TGF-β/BMP-signaling in liver EC to maintain homeostasis and to protect from liver fibrosis." (PMID 33745018, 2021). "Previous studies showed that ERG or FLI1 expression was downregulated in atherosclerosis, systemic sclerosis, pulmonary arterial hypertension, and liver fibrosis." (PMID 30500808, 2018). "In contrast, endothelial transcription factor (ETS)-related gene (ERG) protects against EndMT by preferentially driving SMAD1 signalling and repressing SMAD3 activity, whilst ERG genetic ablation drove EndMT and spontaneous liver fibrosis." (PMID 32982772, 2020).
lymphoma (8 papers, 2013 to 2025). A malignant (clonal) proliferation of B- lymphocytes or T- lymphocytes which involves the lymph nodes, bone marrow and/or extranodal sites. "WP1130 (WP) is a small molecule inhibitor of multiple DUBs (USP9X, 5, 14, UCHL5) that increases cl-PARP and poly-Ub accumulation in lymphoma cells and decreases the oncogenic transcription factor ERG, a key driver of PCa27,48." (PMID 30177856, 2018). "Although these compounds are not ERG-specific, they have demonstrated in vitro and in vivo antitumor activity in multiple lymphoma subtypes by disrupting ETS-helicase interactions." (PMID 41509392, 2025). "Notably, ChIP-seq data of lymphoid cancers, including BCP-ALL, showed that RUNX2, ERG, and ETS1 bind to over 70% of the selected 108 loci." (PMID 38926853, 2024).
acute leukemia (7 papers, 2009 to 2024). A clonal (malignant) hematopoietic disorder with an acute onset, affecting the bone marrow and the peripheral blood. "The multivariate regression test had revealed that BAALC and ERG are independent risk factors for acute leukemia, because." (PMID 27335598, 2016). "Current chemotherapy regimens are insufficient for high-risk acute leukemia patients characterized by high ERG expression." (PMID 24504051, 2014). "In acute leukemia, high ERG mRNA expression levels are an independent prognostic factor." (PMID 27335598, 2016). "Thus, understanding the ERG gene regulatory networks responsible for treatment failure and involved in drug resistance at the molecular level will aid in understanding the etiology of high ERG expression in acute leukemia." (PMID 24504051, 2014). "Furthermore, the role of miR-196a as one of the regulators of the ETS transcription factor ERG known as an adverse prognostic factor for acute leukemia has been also reported." (PMID 23967217, 2013). "Brain and acute leukemia, the cytoplasmic gene (BAALC) and ETS-related gene (ERG) are examples of these transcription factors." (PMID 27335598, 2016). "The expression of Wilms tumor-1 (WT1), brain and acute leukemia, cytoplasmic (BAALC) and ETS-related gene (ERG) might be considered as prognostic factors in AML patients." (PMID 33747867, 2021).
metastatic carcinoma (7 papers, 2014 to 2023). A carcinoma which has spread from the original site of growth to another anatomic site. "In contrast, meningiomas, metastatic carcinomas, and AAs were found to have significantly more extensive immunostaining for ERG than normal brain tissue." (PMID 25881913, 2015). "The overexpression of ERG leads to the dysregulation of cell proliferation, differentiation, angiogenesis, inflammation and apoptosis, and it is thereby considered one of the main factors for the transformation from localised to aggressive and metastatic cancer." (PMID 36980776, 2023).
Obesity (7 papers, 2016 to 2024). Accumulation of substantial excess body fat. "The association of obesity with death might be for a specific tumour subtype such as tumours with the TMPRSS2:ERG gene fusion." (PMID 28701188, 2017). "In a separate study of ERG status and obesity, the authors found that increased BMI and waist circumference, particularly in ERG positive patients, was significantly associated with poor survival." (PMID 33562508, 2021). "In a DIO rat model mRNA expression of ERG subunit is significantly reduced, suggesting that ERG/IKr functional expression is altered in obesity, and therefore may contribute to the LQT phenotype seen in clinically obese patients." (PMID 28680407, 2017). "Recent reports have also demonstrated that the expression of the chaperone protein, heat shock protein 90 (Hsp90) plays a role in ERG channel trafficking defects seen in hyperglycemia, suggesting that in patients altered expression of ROS and Hsp90 may contribute to cardiomyopathies of obesity." (PMID 28680407, 2017). "We have shown that a diet rich in saturated fats leading to obesity results in significant upregulation of Cav1.2, HCN4, Kir2.1, NCX1, SERCA2a, and RYR2 mRNA and significant downregulation of ERG mRNA in the left ventricle." (PMID 27747100, 2016).
ovarian carcinoma (7 papers, 2013 to 2023). A malignant neoplasm originating from the surface ovarian epithelium. "Functional enrichment analysis demonstrated that ERG target genes are significantly annotated for ‘cell movement’, ‘breast or ovarian cancer’, ‘angiogenesis’, ‘development of vasculature’, ‘leukocyte migration’, and other pro-inflammatory functions (p-values from 1e-4 to 1e-17)." (PMID 28585919, 2017).
benign prostatic hyperplasia (6 papers, 2008 to 2024). A non-cancerous nodular enlargement of the prostate gland. "TMPRSS2:ERG fusion is an early event in prostate carcinogenesis, it is absent in benign prostate hyperplasia (BPH) and in normal prostate tissues and is considered to be a diagnostic and prognostic marker for PC." (PMID 37628978, 2023).
cervical carcinoma (6 papers, 2011 to 2025). A carcinoma arising from either the exocervical squamous epithelium or the endocervical glandular epithelium. "In this context, the down-regulation of ERG expression observed in cervical cancer tissues treated with AND suggests that AND inhibits cervical cancer progression by impairing blood vessel development and angiogenesis." (PMID 39937205, 2025). "Further studies are required to explore the biological functions and underlying molecular mechanisms of ERG and FASN in cervical cancer." (PMID 30237984, 2018). "In this study, we identified a signature based on ERG and FASN to predict the risk score of each patient and evaluate the outcome in combination with information regarding TNM stage and type of neoplasm in cervical cancer patients." (PMID 30237984, 2018).